CHPF (chondroitin polymerizing factor)
Diseases named in the same sentence as CHPF in open-access papers (continued):
Sharing a sentence is not in itself a finding about the gene and the disease.
CHPF also shares sentences with these, for which no sentence is quoted: laryngeal carcinoma (2 papers); brain glioma (1); colon adenocarcinoma (1); gastric adenocarcinoma (1); glioblastoma (1); leukemia (1); non-small cell lung carcinoma (1); preeclampsia (1); rectum adenocarcinoma (1).